IDO2 (indoleamine 2,3-dioxygenase 2)
Diseases named in the same sentence as IDO2 in open-access papers (continued):
Sharing a sentence is not in itself a finding about the gene and the disease.
influenza (1 paper, 2020). An acute viral infection of the respiratory tract, occurring in isolated cases, in epidemics, or in pandemics; it is caused by serologically different strains of viruses (influenzaviruses) designated A, B, and C, has a 3-day incubation period, and usually lasts for 3 to 10 days. "Together, these data suggest an IDO1-independent role for IDO2 in the antibody response to influenza." (PMID 32973768, 2020). "IDO2 seems to be the dominant player in many B cell-mediated immune responses, with dko mice generally phenocopying the IDO2 ko in models of autoimmune arthritis, influenza, and NP-immunization." (PMID 32973768, 2020). "IDO2 also influenced antibody responses in models of influenza infection and immunization with T cell-independent type II antigens." (PMID 32973768, 2020). "In addition to having reduced autoreactive B cell responses, IDO2 ko mice generated reduced serum antibody titers in response to influenza infection and immunization with the T cell independent type II antigen, NP-Ficoll." (PMID 32973768, 2020). "IDO2 was not required in all models, but specifically mediated B cell antibody production in response to influenza infection and immunization with a T cell-independent type II model antigen." (PMID 32973768, 2020). "Together, these data demonstrate that IDO2 does not affect all B cell responses, but specifically mediates antibody responses to influenza and T cell independent type II antigens." (PMID 32973768, 2020).
leiomyoma (1 paper, 2022). A well-circumscribed benign smooth muscle neoplasm characterized by the presence of spindle cells with cigar-shaped nuclei, interlacing fascicles, and a whorled pattern. "The mRNA levels of other tryptophan metabolizing enzymes, IDO1 and IDO2, were low and not significantly different, suggesting that TDO2 is the key enzyme responsible for reduced tryptophan levels in mut-MED12 leiomyoma." (PMID 35064560, 2022).
liver cirrhosis (1 paper, 2024). "The liver cirrhosis reduced Tdo2, indoleamine‐2,3‐dioxygenase 1 (Ido2) and kynurenine 3‐monooxygenase (Kmo) mRNA levels in the liver, as well as liver NAD+, plasma NAM and intestinal NAD+ levels in mice." (PMID 39119946, 2024).
lung adenocarcinoma (1 paper, 2023). A carcinoma that arises from the lung and is characterized by the presence of malignant glandular epithelial cells. "In this study, the A549 human cell line, basally expressing IDO2, was used as an in vitro model of human lung adenocarcinoma to gain more insights into a possible alternative function of IDO2 different from the catalytic one." (PMID 38003426, 2023).
Mycobacterium infection (1 paper, 2022). Infections with bacteria of the genus Mycobacterium. "IDO activity is regulated by Mycobacterium infection and host gene polymorphisms, especially in IDO1 and IDO2, and the balance of their expression in TB." (PMID 35045867, 2022).
Nephroblastoma (1 paper, 2024). An embryonal neoplasm characterized by the presence of epithelial, mesenchymal, and blastema components. "Finally, the results showed that there were significant differences in CD80, CD48, IDO2, CD276, CD28, and CD200R1 between both groups, which could be used as potential therapeutic targets for the treatment of nephroblastoma." (PMID 38526609, 2024).
neuropathy (1 paper, 2018). A disorder affecting the nervous system that manifests with pain, tingling, numbness, and/or muscle weakness. "In our opinion, IDO2 is a new and important target for neuropathy treatment, nevertheless, this requires further in-depth research." (PMID 30050435, 2018). "The results of our studies show that the kynurenine pathway is an important mediator of neuropathic pain pathology in rats and indicate that IDO2 and KMO represent novel pharmacological targets for treating neuropathy." (PMID 30050435, 2018). "The results of our studies show that the IDO2 and KMO enzymes of the kynurenine pathway are important for the development of neuropathic pain and indicate that they represent a novel pharmacological target for the treatment of neuropathy." (PMID 30050435, 2018).
pneumonia (1 paper, 2025). An acute, acute and chronic, or chronic inflammation focally or diffusely affecting the lung parenchyma, caused by an infection in one or both of the lungs (by bacteria, viruses, fungi, or mycoplasma.). "Its isoform, IDO2, is also expressed, with IDO1 linked to early-to-mild pneumonia and IDO2 prevalent in more severe and fatal presentations." (PMID 40949107, 2025).
prostate carcinoma (1 paper, 2025). A carcinoma that arises from epithelial cells of the prostate gland. "Given that formyl-kynurenine was significantly upregulated by ADT, it is highly likely that ADT may induce IDO1 and/or TDO2 expression in prostate cancer (IDO2 has been reported to be expressed mainly in immune cells)." (PMID 40759641, 2025).
Stroke (1 paper, 2023). Sudden impairment of blood flow to a part of the brain due to occlusion or rupture of an artery to the brain. "The present study examined for the first time the role of gene polymorphisms of IDO (IDO1 and IDO2) and its inducer and serum IDO1 levels in the risk of PSD at 2 weeks after stroke onset and also discussed the relationship between cytokine SNPs and serum IDO1 levels." (PMID 36911716, 2023).
type 1 diabetes (1 paper, 2025). "In type 1 diabetes models, the downregulation of presynaptic 5‐HT1AR enhances spinal 5‐HT release, reduces quinolinic acid levels, inhibits tryptophan 2,3‐dioxygenase (Tdo), indoleamine 2,3‐dioxygenase (Ido) 1, and Ido2 expression, and improves neuronal degeneration and pain‐related behaviors." (PMID 40937192, 2025).
tumor (70 papers, 2006 to 2025). "In a previous study on non-small cell lung cancer (NSCLC) tissues, we found that IDO2 expression revealed at the plasma membrane level of tumor cells was significantly associated with poor prognosis." (PMID 38003426, 2023). "Other associations with no obvious link to kynurenine include SH2B3 (rs3184504, P = 6.05×10‐18), which is also associated with tumor occurrence and development and IDO2 (rs10085935, P = 3.33×10‐9)." (PMID 35494045, 2022). "As a matter of fact, the expression of IDO2 gene variants is protective in PDAC but increases the risk of developing tumor in NSCLC patients." (PMID 33968089, 2021). "Intriguingly, IDO2 expression was mainly associated with the basolateral side of the tumor cell membrane, and only few cells stained for IDO2 in the cytosol or nucleus." (PMID 33968089, 2021). "IDO1 and IDO2 are members of tryptophan catabolic pathways expressed by tumor cells and tumor microenvironment cells (dendritic cells, macrophages, endothelial cells, tumor-associated Fibroblasts)." (PMID 38260202, 2023). "Furthermore, IDO1 or IDO2 deficiency can modulate the tumor microenvironment by reducing KTR, enhancing immune cell infiltration and IFN-γ production." (PMID 34422661, 2021). "Unexpectedly, the impact of IDO2 loss in tumor growth was mainly associated with females." (PMID 33968089, 2021). "In the pre-clinical setting, blockade of PDL1 led to a strong anti-tumor effect and was associated with an intratumoral inflammatory cytokines signature driven by Ifng but also with a modulation of the KP enzymes including Ido1 and Ido2." (PMID 32194552, 2020). "A unique feature of the IDO2 gene in humans is the high prevalence of two inactivating SNPs, which allow the opportunity to carry out loss-of-function studies directly in humans and to compare patients’ data with those from Ido2−/− and Ido2+/+ tumor-bearing mice." (PMID 33968089, 2021). "In contrast, AhR and IDO2 demonstrated hardly any correlations with clinical or tumour characteristics." (PMID 40471422, 2025). "We observed that IDO2 expression was significantly positively correlated with the percentage of tumour cells (r = .455, p < .001) and inversely correlated with macrophage infiltration (r = –.260, p = .001) (Supplement 10)." (PMID 40471422, 2025). "To better understand these spatial dynamics of IDO2–AhR signaling, we conducted an explorative multiplex immunofluorescence on selected tumour and immune cell markers." (PMID 40471422, 2025). "IDO2 expression demonstrated a strong correlation with the percentage of tumour cells (r = .448, P < .001, Supplement 10)." (PMID 40471422, 2025). "In contrast, both AhR and IDO2 had hardly any correlation with patient, blood or tumour characteristics." (PMID 40471422, 2025). "In vivo, IDO2 silencing via shRNA delays tumorigenesis and suppresses tumor growth, indicating a role for IDO2 in promoting the tumor cell cycle." (PMID 40103267, 2025). "Instead, we observed consistent co-expression between IDO2 and AhR, particularly in tumour-dense regions, suggesting a role in sustaining immunosuppression." (PMID 40471422, 2025). "Research on IDO2 in GBM is limited, but it has been implicated in immune evasion through the Kyn–AhR pathway in multiple tumour types." (PMID 40471422, 2025). "In contrast to both IDO1 and TDO, gene expression of IDO2 is limited in human tumor tissues, and tryptophan-metabolizing activity fully resides with co-present IDO1 in IDO2-expressing tumors." (PMID 39211039, 2024). "It is worth noting that IDO1, IDO2, CD44, and CD200 are up-regulated in the FRM high-risk group, all of which are related to the tumor microenvironment." (PMID 38534739, 2024). "Within the IDO2 protein, they identified HLA-A2 peptides targeted by spontaneous T-cell reactivity in patients suffering from unrelated tumor types." (PMID 39594642, 2024).
tumor (continued). "IDO1 is predominantly found in glial cells, neurons, microglia, DCs, monocytes, and macrophages, whereas IDO2 is primarily expressed in certain tumor cells." (PMID 39492834, 2024). "Its specific role and mechanisms are still being elucidated, but the IDO2 involvement in various neoplastic diseases makes this protein a promising target for future cancer therapies, and a potential biomarker and prognostic factor as well." (PMID 39594642, 2024). "Silencing Ido2 in murine dendritic cells inhibits the tumor growth in vivo, promotes the proliferation of T lymphocytes, and reduces the formation of regulatory T cells in vitro." (PMID 39594642, 2024). "In the same study, 83% of tumors showed a membrane reinforcement staining of IDO2 that, in 51% of cases, localized at the basolateral side of the cell membrane between tumor and stromal tissue." (PMID 39594642, 2024). "Despite the prominent role of the paralog IDO1 in immune cells (besides cancer and tumor microenvironment cells), little is known about the expression and the role of IDO2 in the human immune system." (PMID 39594642, 2024). "Protein expression predominantly clustered within high-density tumor cell regions, notably with AhR and IDO2 demonstrating markedly elevated levels compared to IDO1 and TDO2." (PMID 38951170, 2024). "These pieces of evidence suggest that IDO2 plays a role in cancer biology, particularly in cell cycle regulation, tumor progression, and cell proliferation." (PMID 39594642, 2024). "As for other neoplastic diseases, IDO2 is frequently upregulated in human pancreatic ductal adenocarcinoma (PDAC)." (PMID 39594642, 2024). "In some tumors, IDO2 expression has also been observed in non-tumor tissues adjacent to the neoplastic masses." (PMID 39594642, 2024). "These receptors promote xenobiotic metabolism by inducing the cytochrome enzymes, and they induce IL-6, which can induce further IDO1, IDO2 or TDO in malignant cells or tumor lines." (PMID 37296860, 2023). "The selective inhibition of IDO2 will be of particular interest, as it promotes expression of IFNγ and increases effector cell invasion of the tumor microenvironment, suppressing growth and cell migration." (PMID 37296860, 2023). "Although there has been a strong emphasis on understanding the role of IDO1 or IDO2 in tumor viability, there is increasing attention to downstream enzymes such as KMO." (PMID 37296860, 2023). "FOXM1 stimulates indoleamine 2,3 dioxygenase (IDO2) which stimulates T-reg cells which are immunosuppressive and induce tumour tolerance." (PMID 35354487, 2022). "At the same time, the expression level of IDO2 has nothing to do with the age range, heredity, unilateral and bilateral lesions, and maximum tumor size." (PMID 36319978, 2022). "In tumor tissues, IDO2 contributed to IDO1-mediated immune tolerance and functioned as a negative regulator of IDO1 by competing with it for the heme binding site." (PMID 35045867, 2022). "Evidence from previous studies suggests that tumours prefer to up-regulate TDO2 more than IDO1 or IDO2." (PMID 36286592, 2022). "The silencing of IDO2 in DC not only negatively regulated the growth of tumor cells but also helped to improve the immunotherapeutic effect of DC-based cancers." (PMID 35571564, 2022). "The authors show that the silencing of IDO-2, achieved through a small interfering RNA (siRNA), inhibits the proliferation of tumor cells, stops the cell cycle in G1, induces greater cell apoptosis and reduces cell migration in vitro." (PMID 33671892, 2021). "We studied gene expression levels of immune-related genes PD-1, PD-L1, PD-L2, IDO-1, IDO-2 and INFγ in tumor tissue of surgically resected NSCLC and correlated the finding with clinicopathological features and patient outcomes." (PMID 33671892, 2021).
tumor (continued). "Our efforts concentrated on developing an immune signature with prognostic ability based on the comprehensive list of immune-related genes (PD-1, PD-L1, PD-L2, IDO-1, IDO-2 and INFγ) and then examining gene expression in the tumor microenvironment." (PMID 33671892, 2021). "Regarding the expression of IDO-1 and IDO-2, several studies show that their role can influence tumor progression." (PMID 33671892, 2021). "These cells showed increased expression of genes related to tumor growth (Cox2 and Vegfa), metastasis (Cox2, Mmp2, and Mmp9), and immune suppression (Ido2), indicating that TAM generation in vitro had been successful." (PMID 34900687, 2021). "In the lung parenchyma, IDO2 marked reactive pneumocytes close to tumor tissue and also intralveolar macrophages." (PMID 32536910, 2020). "Our purpose is to evaluate the level of IDO2 through its immunohistochemical expression in a series of resected NSCLCs, in order to assess its presence and localization in the tumor cells of this specific type of cancer." (PMID 32536910, 2020). "Correlations between IDO2 expression, clinical-pathological data, tumor-infiltrating lymphocytes (TILs), immunosuppressive tumor molecules (IDO1 and programmed cell death ligand-1 – PD-L1 –) and patients' prognosis were evaluated." (PMID 32536910, 2020). "Our previous studies have demonstrated that gene silencing of IDO2 can induce B16-BL6 tumor cell apoptosis." (PMID 32582152, 2020). "Another interesting and incidental finding is that 10% of NSCLCs presented a nuclear pattern of IDO2 staining in tumor cells." (PMID 32536910, 2020). "Together, the IDO1 and IDO2 genes are variably upregulated in neoplastic cells as well as in stromal, endothelial, and innate immune cells of the tumor microenvironment and in tumor-draining lymph nodes." (PMID 30806743, 2019). "The data we show here reveals the new immune-independent function of IDO2 in mediating tumor formation and growth." (PMID 27058624, 2016). "We investigated the effect of IDO2 on the physiological and pathophysiological functions of tumor cells, including cell proliferation, migration, apoptosis and cell cycle." (PMID 27058624, 2016). "We further demonstrated that cell apoptosis, induced by IDO2 downregulation, can be attenuated by addition of exogenous NAD+, suggesting a novel mechanism by which IDO2 promotes tumor growth through its metabolite product NAD+." (PMID 27058624, 2016). "To determine the role of IDO2 in tumor growth in vivo, we first generated an IDO2 shRNA transfected stable cell line." (PMID 27058624, 2016). "Tumor growth was significantly slower in IDO2 shRNA treated mice compared with scrambled shRNA treated mice." (PMID 27058624, 2016). "Next we investigated the effect of differential expression levels of IDO2 in tumor cells on tumor formation and growth in vivo." (PMID 27058624, 2016). "We observed that tumor onset in IDO2 shRNA stable cells (B16-BL6/IDO2-) injected mice was substantially postponed compared with mice injected with scrambled shRNA cells (B16-BL6/IDO2+)." (PMID 27058624, 2016). "We further demonstrate that cell apoptosis, induced by IDO2 downregulation, can be weakened by addition of exogenous NAD+, suggesting a novel mechanism by which IDO2 promotes tumor growth through its metabolite product NAD+." (PMID 27058624, 2016). "D-1-MT was shown to have superior anti-tumor activity in preclinical models, suggesting the important role of IDO2 in cancer development." (PMID 27058624, 2016). "Like IDO1, IDO2 is an immunosuppressive molecule, and it plays an important role in induction and maintenance of tumor microenvironment immune tolerance." (PMID 27058624, 2016). "Furthermore, tumor microenvironment induces imDCs to secret suppressive factors like Il-10, Arg1, Ido1 and Ido2." (PMID 40730800, 2025).